ACE (angiotensin I converting enzyme)
Diseases named in the same sentence as ACE in open-access papers (continued):
Sharing a sentence is not in itself a finding about the gene and the disease.
COVID-19 (continued). "In this sense, genetic variants of ACE and ACE2 could explain the observed interindividual variability to COVID-19 outcomes." (PMID 35250987, 2022). "It is important to note that human clinical studies have not identified ACE inhibitors or ARB medications to be risk factors for susceptibility to or poor outcome from COVID-19." (PMID 35359831, 2022). "However, currently there are no studies that address the potential benefits and harms of initiating ACE inhibitors or ARBs as treatment for patients with COVID-19." (PMID 33025384, 2021). "Next, we investigated the ACE serum activity of COVID-19 patients in a genotype-specific manner." (PMID 35095487, 2021). "Although many patients with cardiovascular diseases are treated with ACE inhibitors or angiotensin receptor blockers, no negative impact of these drugs on the risk for severe COVID-19 was found." (PMID 35498160, 2021). "The disturbed balance of the ACE/AngII/AT1R axis in COVID-19 patients might also contribute to the thromboembolic complications often seen in these patients." (PMID 33824998, 2021). "In addition to COVID-19 vaccines, iBio is developing a COVID-19 therapeutic ACE-Fc, ACE2 fused with the Fc region of human IgG1, in collaboration with Planet Biotechnology." (PMID 34579229, 2021). "This theory is epidemiologically supported by a negative correlation between the prevalence of COVID-19 and the ACE D-allele frequency." (PMID 33390179, 2021). "Accordingly, it is speculated that therapeutics to suppress the RAS, such as angiotensin-receptor blockers (ARBs) and ACE inhibitors, might also be beneficial for COVID-19 patients." (PMID 34815389, 2021). "Early in the pandemic, various reports suggested that ARBs and ACE inhibitors might be associated with increased susceptibility to SARS-CoV-2 infection and worse outcomes for COVID-19 cases." (PMID 34338794, 2021). "Although it is unclear if the ACE inhibitor really works on COVID-19, the consensus is that inhibiting the interaction between ACE2 and the spike protein of COVID-19 could stop the infection." (PMID 33671652, 2021). "The ACE/ACE2 activity ratio has shown to be lower in serum samples of females compared to male serum samples, and the lower ACE/ACE2 activity ratio could be one of the factors that protect female COVID-19 patients from developing severe complications." (PMID 33969006, 2021). "ACE activation promotes the accumulation of angiotensin II, which could be pathologically involved in both COVID-19 and RA." (PMID 34943795, 2021). "Various authors have hypothesized carotid body (CB) involvement in Coronavirus Disease 2019 (COVID-19), through direct invasion or indirect effects by systemic stimuli ('cytokine storm', angiotensin-converting enzyme [ACE]1/ACE2 imbalance)." (PMID 34764954, 2021). "One potential includes the development of PD models relating the extent of ACE inhibition to Ang II levels (postulated to play a role in the “cytokine storm” secondary to COVID-19) that could drive hypothesis-driven modeling and simulation of patient outcomes." (PMID 33805419, 2021). "Evidence on the effect of NSAIDs and ACE inhibitors on COVID-19 outcomes remains inconclusive." (PMID 34006330, 2021). "Finally, we used spatial transcriptomics to map ACE expression in SARS-CoV-2 infected lungs from COVID-19 patient autopsies." (PMID 33712587, 2021). "RAS (Renin-Angiotensin System) signaling pathway: The inhibition of ACE (Angiotensin Converting Enzyme) connected to RAS signaling pathway could reduce tissue damage in COVID-19 patients." (PMID 33953223, 2021). "Our results showed that reduced ACE activity in the COVID-19 patients may be due to the dynamic changes of ACE2 activity during the different stages of lung injury, which induce further imbalance of RAAS and accelerate the progression of the disease." (PMID 35095487, 2021).
COVID-19 (continued). "A systematic literature search was performed to answer the question: What is the effect of medications that influence ACE2 expression (ACE inhibitors (ACEIs), angiotensin receptor blockers (ARBs), nonsteroidal anti-inflammatory drugs (NSAIDs) and thiazolidinediones) on the outcomes of COVID-19?" (PMID 33860910, 2021). "The use of ACE inhibitors or ARBs did not increase the risk of adverse COVID-19 outcomes, supporting current guidance to continue these medications when indicated." (PMID 34059140, 2021). "The optimistic outcomes of fetal-derived stem cell therapy for COVID-19 treatment might be due to having a higher proportion of active stem cells and a lower ratio of ACE/ACE2 in fetal-derived MSCs compared to other adult tissue-derived stem cells." (PMID 34769218, 2021). "In view of the fact that majority of the participants in the studies are originated from China or Asian countries, researches from non-Asian countries should also be conducted to secure more generalized and accepted utilization of ACE-inhibitor or ARB in hypertensive COVID-19 patients." (PMID 33544293, 2021). "Additionally, the treatment of ACE inhibitors or ARB was effective on COVID-19 patients with lower complications." (PMID 33920748, 2021). "It was also proposed that ACE and Angiotensin II may be a therapeutic target for COVID-19 patients through their effects on the previously discussed polymorphisms." (PMID 33748156, 2021). "The respective activities, however, increased in the recovery phase, and the authors concluded that serum ACE activity could be potentially used as a marker to reflect severity of COVID-19 at baseline." (PMID 34358119, 2021). "A cohort study including 8.3 million people showed that neither ACE inhibitors nor ARBs are associated with increased risks of severe forms of COVID-19 and ICU admission." (PMID 34829920, 2021). "It was suggested a protective role of ACE2 upregulation and ARBs/ACE inhibitors treatment in COVID-19 and raised concerns that ARBs/ACE inhibitors treatment could promote SARS- CoV-2 infection by increasing the expression of ACE2." (PMID 34912542, 2021). "After multivariable adjustment, neither ACE inhibitors nor ARBs showed an association with the risk of developing COVID-19 (OR 0.95 [95% CI 0.86 to 1.05] and 0.96 [95% CI 0.87 to 1.07], respectively." (PMID 33722197, 2021). "Then, we speculate that by utilizing the alkaloids in BFC to act on lung injury, lung inflammation, ACE target, immunoregulation, oxidative stress, and so on, is there a potential drug in the treatment of COVID-19?" (PMID 35126123, 2021). "In our cohort of COVID-19 patients, serum ACE activity was similar in both groups." (PMID 34358119, 2021). "Although the application of ACE inhibitors/angiotensin-receptor blockers is increasingly being considered for COVID-19, such molecules may unfavourably alter the balance between ACE and ACE2." (PMID 34102081, 2021). "The American Heart Association does not advise the initiation of ACE blockers and that its use should be stopped in COVID-19 patients." (PMID 34650947, 2021). "Although angiotensin-converting enzyme (ACE) and ACE2 are distinct enzymes with different mechanisms of action, ACE2 has been linked to susceptibility to COVID-19 as well as its severity, as the viral protein involved in cell entry (spike S protein) binds to ACE2." (PMID 33496668, 2021). "ACE genotype frequencies of COVID-19 patients in ICU who survived or who died." (PMID 34489863, 2021). "This fact raised concerns regarding the utilization of ACE inhibitors and ARBs which may exacerbate severity of COVID-19 patients." (PMID 33544293, 2021). "Recent ecological studies of COVID-19 report that countries with high consumption of foods with potent antioxidant or anti angiotensin-converting enzyme (ACE) activity such as raw or fermented cabbage have a lower COVID-19 death rate compared to other countries." (PMID 34203027, 2021).
COVID-19 (continued). "The information that ACE inhibitors and AT1R blockers may increase the risk of SARS-CoV-2 infection and adversely affect the course of COVID-19 was disseminated quite quickly by global social media and caused some confusion in the medical community." (PMID 33925881, 2021). "Gut microecological disorders in patients with COVID-19 may be closely related to the loss of ACE2 and the overactivation of the ACE/AngII/AT1R (angiotensin II receptor type 1) axis." (PMID 35004750, 2021). "Various large cohort studies have suggested that the use of ACE inhibitors was not correlated with increased SARS-CoV-2 infection but was in fact linked to a reduced risk of mortality in hospitalized COVID-19 patients." (PMID 34769093, 2021). "Regarding the role of renin-angiotensin system (RAS) inhibitors in the outcome of COVID-19 infected non-RTRs, we have found that ACE/ARB treatment history is associated with mortality in this group." (PMID 34876176, 2021). "The controversial pathogenesis as well as the mixed results of several clinical studies of pneumonia with other pathogens made it difficult for physicians to determine whether the use of ACE inhibitors or ARBs should be terminated in patients with COVID-19." (PMID 34490373, 2021). "Elucidation of the impact of RAS elements, including ACE, could be helpful for better understanding the pathobiology of COVID-19 as well as the clinical management of patients infected with SARS-CoV-2." (PMID 34603503, 2021). "Therefore, we should be more vigilant when it comes to the cardiac condition of COVID-19 patients in clinical practice, complying with the principles of individualization in the application and selection of ACE inhibitor-like drugs for these patients." (PMID 33573324, 2021). "Thus, reduced expression of ACE2 in the kidneys, which reduces the ACE/ACE2 ratio, has been suggested as a possible cause of local vasoconstriction and inflammation, necrosis, and kidney damage in COVID-19 patients." (PMID 34564326, 2021). "The ACE-AngII-AT1 axis may be activated in the COVID-19 patients, given that there was a higher immunoexpression of AKT-1 and TGF-β1 in those patients compared to the CONTROL group." (PMID 35008594, 2021). "However, there is not adequate evidence to confirm the risk or beneficial effects of ABRs, ACE inhibitors, thiazolidinediones (TZDs), or GLP-1 agonists in COVID-19 patients." (PMID 34205044, 2021). "In addition, demographic studies have found in the racial variance of ACE I/D genotype a potential explanation of the different prevalence and outcomes due to COVID-19." (PMID 33585520, 2020). "According to a recent study, the lack of statistically validated data precluded an unambiguous statement on whether ACE inhibitors or ARBS improve or worsen the severity of COVID-19 patients." (PMID 32719619, 2020). "In line with previous studies, we speculated that the decreased serum ACE activity in severe COVID-19 was attributed to the injured pulmonary endothelium." (PMID 33238910, 2020). "We obtained 251 potential therapeutic targets of COVID-19 from the GeneCards database, 119 therapeutic targets were obtained from the systemic literature search and Single-cell sequencing was used to obtain 3525 gene targets that were co-expressed with ACE." (PMID 33082858, 2020). "On the contrary, others contemplate that ACE inhibitors/angiotensin 2 receptor blockers (ARBs) may decrease the severity of COVID-19 and have beneficial effects." (PMID 32851877, 2020). "Recent study report that local or systemic infection may lead acute lung injury and vasoconstriction via involvement of ACE, angiotensin I and II system in various respiratory diseases including COVID-19." (PMID 32916821, 2020). "ACE mediates the breakdown of bradykinin to its inactive peptides and increased aldosterone-induced ACE expression in COVID-19 may inactivate bradykinin, consequently preventing bradykinin-mediated increase in tPA." (PMID 33375371, 2020).
COVID-19 (continued). "There have been hypothesized that the use of ACE-inhibitors and angiotensin receptor 1 blockers (ARBs) may have effect the course of COVID-19." (PMID 33261654, 2020). "Supporting this perspective, a population-based case-control study reported that the use of ACE inhibitors or ARBs does not directly correlate with COVID-19 susceptibility or outcome severity." (PMID 33414783, 2020). "Therefore, we performed a retrospective study to explore the clinical significance of serum ACE activity in COVID-19." (PMID 33238910, 2020). "Although there is concern that inhibition of ACE2 activity may promote an excessive inflammatory response resulting from an increase in Ang II, ACE inhibitors can be considered as a treatment option for COVID-19 in two respects." (PMID 33218024, 2020). "Moreover, it is interesting that COVID-19, ACE, and FVIII positivity were collected in the same fields." (PMID 32784826, 2020). "It is possible that ACE inhibitors may reduce the down regulation of ACE2 receptors via reducing ANG II formation in COVID-19." (PMID 32685191, 2020). "From the pathophysiological point of view, the spike protein in the morphology of COVID-19 bind to angiotensin-converting enzyme (ACE)-receptors on alveolar epithelial cell type 2 (AT2), primed by transmembrane protease serine 2 (TMPRSS2) to allow coronavirus entry." (PMID 33708124, 2020). "Therefore, discontinuation or alternative antihypertensive drugs have been suggested for COVID-19 patients treated with ACE inhibitors or angiotensin-receptor blockers (ARBs)." (PMID 33365277, 2020). "It is possible, therefore, to speculate that reduced use of ACE inhibitors in women also provides reduced protection from COVID-19; at the same time, greater exposure to diuretics could increase the risk of hypokalemia." (PMID 33022004, 2020). "There is tremendous interest in the risks and benefits of medications such as ACE inhibitors and ARBs for COVID-19, and whether other medications, such as ibuprofen, should be avoided." (PMID 33024121, 2020). "Therefore, the COMET study aims to evaluate the relationship between use of certain drugs, starting with ACE inhibitors and ARBs, on clinical outcomes of patients with COVID-19." (PMID 32587077, 2020). "In our study ACE, REN, INS, KNG1, and AGT showed the highest connectivity within the complete ACE2 network and association with enriched diseases that are known to be a risk factor for a severe course of COVID-19." (PMID 33233425, 2020). "It is also known from previous studies that the disruption of the skin barrier can provide a route of entry for the coronavirus as the angiotensin-converting enzyme (ACE-2)—the cell receptor for COVID-19—is present in hair follicles, the epidermis, and the blood vessels of the skin." (PMID 33376481, 2020). "However, much like COVID-19, the impact of ACE inhibitors on survival outcomes with ICIs is currently unclear." (PMID 33344513, 2020). "If so, ACEIs and ARBs may have a beneficial effect on the course of COVID-19 by reducing ACE/AngII/AT1R signalling and thereby restoring the local balance between the activities of the ACE/AngII/AT1R and ACE2/Ang1–7/MasR axes." (PMID 32514935, 2020). "It was proposed that ACE inhibitors could have both potentially harmful and beneficial effects on COVID-19." (PMID 32842509, 2020). "A number of studies have reported the effect of ACE inhibitors on COVID-19 prognosis." (PMID 33362779, 2020). "The reason for suspicion that some drugs might worsen the prognosis of COVID-19 stems from current reports that, for example, ACE inhibitors may lead to an increase in the number of ligands to which the SARS-CoV-2 coronavirus docks." (PMID 32415494, 2020). "Finally, Scientific Societies have expressed their opinion on the use of RAS inhibitors, highlighting the absence of evidence suggesting an eventual discontinuation of ACE-inhibitors, or ARBs in patients with COVID-19." (PMID 32850989, 2020).
COVID-19 (continued). "Up to now, no study has investigated the involvement of ACE I/D polymorphism in COVID-19 complicated by pulmonary embolism, hence the aim of the present pilot study." (PMID 33585520, 2020). "Notably, hypertensive (the most frequent comorbidity with COVID-19) and diabetic patients are often treated with ACE inhibitors (ACEIs) and/or with ARBs, suggesting a possible positive correlation." (PMID 32708755, 2020). "Thus, it is necessary to further explore the potential impact of ACE inhibitors and ARBs on the pathogenesis and prognosis of COVID-19." (PMID 33199670, 2020). "The expression of ACE-2 was more prevalent in Asian men, which could explain the higher prevalence of COVID-19 in this group of patients than in women and patients of other ethnicities." (PMID 32916821, 2020). "However, without the inclusion of clinical phenotypes in the model, we did not observe a significant ACE polymorphism association with COVID-19 severity (likelihood ratio test p = 0.1)." (PMID 41680633, 2026). "In addition, DM itself or its associated treatments, such as angiotensin-converting enzyme (ACE) inhibitors, may influence the severity of COVID-19 by over-expressing the ACE2 receptor, a key entry point for the virus into cells​." (PMID 40314776, 2025). "Thus, the regulation of ACE in EAT may contribute to the cardiac and perivascular inflammation associated with COVID-19 and PACS." (PMID 39200115, 2024). "Moreover, including additional cell types such as pulmonary cells and cardiomyocytes in experimental models could offer a more comprehensive understanding of the cellular mechanisms underlying ACE and other RAS component levels in COVID-19." (PMID 40417281, 2024). "Therefore, the current study demonstrates that the presence of the ACE1 D/D genotype; being associated with higher ACE serum levels; may constitute risk factors for more severe COVID-19 clinical course as well as developing ARF, and ICU admission." (PMID 38177248, 2024). "ACE (AUC: 0.923), CYP1A1 (AUC: 0.902), EME1 (AUC: 0.977), CD52 (AUC: 0.970), MYBL2 (AUC: 0.995), CDC25A (AUC: 0.998), BCL6 (AUC: 0.966) and CD3D (AUC: 0.955) showed relatively good diagnostic efficiency in distinguishing COVID-19 patients from healthy controls." (PMID 38978778, 2024). "Therefore, our results revealed the nonrobustness of our conclusion, so the relationship of COVID-19 risk with the ACE I/D polymorphism should be further investigated." (PMID 38058963, 2023). "Therefore, the imbalance of ACE2/ACE levels in COVID-19 and the dysregulated AngII/AT1R axis may partially be responsible for the cytokine storm and the resulting pulmonary damage." (PMID 36901403, 2023). "Moreover, a systematic review found that ACE and the interferon-induced transmembrane protein 3 (IFTM3) gene polymorphisms may lead to a genetic predisposition for severe lung injury in COVID-19 patients." (PMID 38113267, 2023). "It is noteworthy that ACE, ACE2, and AGTR2 polymorphisms have also been associated with hypertension, diabetes, coronary artery disease, and stroke, which complicates the risk estimation, as those comborbities alone are associated with an increased risk of COVID-19." (PMID 36835445, 2023). "We hypothesized the roles of ACE and ERAP polymorphisms in the prediction of COVID-19 outcomes." (PMID 36673116, 2023). "Moreover, we found that the ACE activity level is impaired in patients with other respiratory diseases but not in the same proportion as the COVID-19 group, since the non-COVID-19 group exhibited a lower enzyme activity when compared to the post-COVID-19 group." (PMID 37108839, 2023). "Finally, at the present time, it is well known that, one of the factors that is responsible for exacerbation of pro-inflammatory cytokines in COVID-19 is the activation of local RAS in the lung leading to generation of Ag-II by ACE that acts on Ang-II receptors." (PMID 37060024, 2023).